PRICKLE3 (prickle planar cell polarity protein 3)
Description:
Involved in the planar cell polarity (PCP) pathway that is essential for the polarization of epithelial cells during morphogenetic processes, including gastrulation and neurulation (By similarity). PCP is maintained by two molecular modules, the global and the core modules, PRICKLE3 being part of the core module (By similarity). Distinct complexes of the core module segregate to opposite sides of the cell, where they interact with the opposite complex in the neighboring cell at or near the adherents junctions (By similarity). Involved in the organization of the basal body (By similarity). Involved in cilia growth and positioning (By similarity). Required for proper assembly, stability, and function of mitochondrial membrane ATP synthase (mitochondrial complex V).
Synonyms: Pk3; LMO6; LOAM; LOAS
Tractability: Antibody: UniProt places it where antibodies can reach, with medium confidence; its Gene Ontology location is reachable by antibodies, with medium confidence. PROTAC: ubiquitination databases record sites on it.
Gene: Protein-coding gene on chromosome X (49,174,802 to 49,186,528, reverse strand). Ensembl gene ENSG00000012211.
Subcellular location: Cytoplasm; Cell membrane; Mitochondrion
Gene Ontology:
Molecular function: protein binding; zinc ion binding
Cellular component: cytoplasm; mitochondrion; plasma membrane
Homologues: Orthologues: chimpanzee PRICKLE3 (99% identical), macaque PRICKLE3 (97% identical), pig PRICKLE3 (92% identical), mouse Prickle3 (90% identical), rat Prickle3 (89% identical), dog PRICKLE3 (88% identical), guinea pig PRICKLE3 (76% identical), zebrafish prickle3 (48% identical), tropical clawed frog prickle3 (44% identical), Drosophila melanogaster esn (43% identical), Drosophila melanogaster pk (43% identical), Caenorhabditis elegans prkl-1 (31% identical). Paralogues in human: PRICKLE2 (48% identical).
Diseases named in the same sentence as PRICKLE3 in open-access papers:
PRICKLE3 is named in the same sentence as 5 diseases in open-access papers, as found by Europe PMC text mining. Sharing a sentence is not in itself a finding about the gene and the disease. The quoted sentences say what the papers report.
cancer (2 papers, 2023). A tumor composed of atypical neoplastic, often pleomorphic cells that invade other tissues. "There are no relevant reports of ZNF79, PRICKLE3, RPAP1, ABHD8, and FBXO33 in cancer, and more research is still needed." (PMID 37274025, 2023).
PRICKLE3 also shares sentences with these, for which no sentence is quoted: bladder cancer (1 paper); cognitive decline (1); cryptorchidism (1); tumor (1).